MTOR (mechanistic target of rapamycin kinase)
Diseases named in the same sentence as MTOR in open-access papers (continued):
Sharing a sentence is not in itself a finding about the gene and the disease.
keloid (continued). "The PI3K/AKT/mTOR pathway is upregulated in keloid tissue, contributing to the excessive collagen production, abnormal fibroblast activity, and resistance to apoptosis that define keloid pathology." (PMID 41424791, 2025). "Targeting the PI3K/AKT/mTOR pathway presents a promising therapeutic approach for keloid treatment, given its central role in controlling fibroblast proliferation, migration, survival, and myofibroblast differentiation, processes fundamental to keloid pathogenesis." (PMID 41424791, 2025). "The addition of phosphatidylinositol 3-kinase (PI3K), mitogen activation protein kinase (MAPK), Specificity protein 1 (Sp1), and mammalian target of rapamycin (mTOR) inhibitors inhibited IL-18 secretion in keloid cocultures, suggesting their potential clinical use in the treatment of keloid." (PMID 39799030, 2025). "This section reviews the latest treatment targeting the PI3K/AKT/mTOR pathway in keloids." (PMID 41424791, 2025). "Also, a recent study suggested that sunitinib effectively inhibits keloid development through suppression of the Akt/PI3K/mTOR pathway." (PMID 39201463, 2024). "In addition, increased angiogenesis and immune cell infiltration are observed in keloids, suggesting the involvement of mTOR pathway, which is a plausible therapeutic target for the management of keloids." (PMID 37371141, 2023). "These suggested the importance of targeting the PI3K/Akt/mTOR axis for treating keloids." (PMID 37371141, 2023). "In addition, IPA revealed that TGF-β, mTOR signaling, endothelin, ErbB, sirtuin, and mitochondrial dysfunction differed between the keloid and the control groups, as reported in a previous study that focused on the mechanism of keloid formation." (PMID 34639105, 2021). "Rapamycin, an mTOR inhibitor, is known to have therapeutic efficacy in keloid." (PMID 33126764, 2020). "The results showed Wubeizi ointment could reduce the size of keloid morphologically in nude mice and could influence the expression pattern of some key factors involved in the mTOR pathway both in the keloid tissues and in cultured keloid fibroblast cells." (PMID 33062677, 2020). "We used IGF-1, an agonist of the mTOR signaling pathway, to activate the mTOR signaling pathway after adding Wubeizi ointment, and then the proliferation of keloid fibroblasts was detected to test whether the drug efficacy is inhibited." (PMID 33062677, 2020). "In the present study, we investigated if Wubeizi ointment suppressed keloid formation through the modulation of key molecules of the rapamycin (mTOR) pathway including phosphatase and tensin homolog (PTEN), phosphatidylinositol 3-kinase (PI3K), and protein kinase B (Akt)." (PMID 33062677, 2020). "This can confirm whether the mechanism of Wubeizi ointment regulates the mTOR signaling pathway to inhibit the proliferation of keloid fibroblasts." (PMID 33062677, 2020). "The current study explored if Wubeizi ointment could suppress keloid formation through the modulation of the mTOR signaling pathway." (PMID 33062677, 2020). "The results of qPCR and western blot showed that, compared to the control group, mRNA of Akt1, and phosphorylated protein levels of Akt, mTOR significantly decreased in keloid tissues from the Wubeizi ointment-treated group, and the effect is dose-dependent (P < 0.05)." (PMID 33062677, 2020). "Synthetic drugs targeting the PI3K/AKT/mTOR pathway have essential roles in managing keloid formation by interfering with the intracellular signaling mechanisms that modulate cell growth, proliferation, and survival, all of which are hyperactive in keloid fibroblasts." (PMID 41424791, 2025). "Thus, sunitinib may effectively inhibit keloid development through inhibition of the Akt/PI3K/mTOR pathway." (PMID 38046417, 2023).
keloid (continued). "Furthermore, similar findings have been reported where inhibition of mTOR protein expression in keloid fibroblasts can also inhibit the migratory ability of keloid fibroblasts and thereby further inhibiting the development of keloids." (PMID 34359971, 2021). "Therefore, we hypothesized the possibility that Wubeizi ointment could act via the mTOR signaling pathway to inhibit the formation of keloid scar." (PMID 33062677, 2020). "Phosphorylation of the ribosomal protein S6, a marker of mTOR (a mammalian target of rapamycin) pathway activation, is strongly increased in hypertrophic scars and keloids; RAPA is the inhibitor of mTOR, which could downregulate the expression of collagen and fibronectin." (PMID 27094512, 2016). "It reduces phosphorylation of mTOR and downstream effectors (p70S6K, S6, 4E-BP1), leading to dose-dependent decreases in collagen I and III expression in both normal and keloid fibroblasts." (PMID 41424791, 2025). "The lncRNA uc003jox. promotes keloid fibroblast proliferation and invasion by activating the PI3K/AKT/mTOR pathway." (PMID 41424791, 2025). "The 1O2 not only result in endogenous ferroptosis by destroying the ferritin, but also give rise to synergistic photodynamic therapy that can effectively combat keloids through inhibiting the PI3K-AKT and mTOR pathways while activating the ferroptosis pathway." (PMID 40521195, 2025). "In keloids, abnormal activation of the PI3K/Akt/mTOR signaling pathway is considered a key factor leading to excessive proliferation of fibroblasts and increased collagen synthesis." (PMID 40718487, 2025). "In keloids, DJ-1 inactivates PTEN via redox-dependent S-nitrosylation, thereby activating PI3K/AKT/mTOR signaling, which enhances fibroblast proliferation, migration, invasion, and collagen overproduction." (PMID 41424791, 2025). "Its expression depends on PI3K/mTOR, MAPK, and Sp1 pathways, making IL-18 a key mediator of fibroblast activation and a potential therapeutic target in keloid scarring." (PMID 41424791, 2025). "Mast cells, for instance, interact with fibroblasts to enhance collagen production through pathways such as PI3K/Akt/mTOR and TGF-β1/Smad, contributing to the persistent fibroblast activation seen in keloids." (PMID 39201463, 2024). "Nrf2-mediated oxidative stress response, mTOR signaling, EIF2 signaling, BMP signaling, mitochondrial dysfunction, and necroptosis signaling were more enriched in keloids than in normal tissues." (PMID 34639105, 2021). "Natural products offer multifaceted therapeutic potential in keloid management by modulating fibroblast proliferation, collagen synthesis, inflammation, and key signaling pathways such as TGF-β/Smad, IL-6/STAT3, and PI3K/Akt/mTOR." (PMID 41424791, 2025). "Pathological scars, such as hypertrophic scars (HTSs) and keloids, result from aberrant fibroblast proliferation, resistance to apoptosis, and dysregulated signaling pathways, particularly the TGF-β1/Smad and PI3K/Akt/mTOR cascades." (PMID 40733118, 2025). "Its elevated expression enhances phosphorylation of PI3K, AKT, and mTOR while suppressing apoptosis, whereas uc003jox. knockdown upregulates PTEN and attenuates pathway activation, identifying it as a key pro-fibrotic regulator in keloid pathogenesis." (PMID 41424791, 2025). "Its upregulation in keloid tissue enhances cell growth and angiogenic activity, whereas H19 knockdown suppresses proliferation and downregulates mTOR and VEGF expression, identifying H19 as a key pro-fibrotic regulator and potential therapeutic target in keloid pathogenesis." (PMID 41424791, 2025). "Similarly, melatonin regulates keloid fibroblast activity mainly through MT2 receptor–mediated inhibition of the cAMP/PKA/Erk and Smad pathways, with minimal impact on Akt/mTOR signaling." (PMID 41424791, 2025). "In addition, the expression of mTOR and its upstream molecules PI3K and Akt were significantly increased in keloid tissues." (PMID 33062677, 2020).
keloid (continued). "Similarly, CD26 drives keloid fibroblast proliferation and invasion through IGF-1/IGF-1R-mediated PI3K/Akt/mTOR activation, promoting mTOR downstream effectors (P70S6K, 4E-BP1); inhibition of CD26 or IGF-1R abrogates these effects, underscoring their central role in keloid progression." (PMID 41424791, 2025). "We aimed to investigate the effects of silibinin on collagen expression in normal human dermal and keloid-derived fibroblasts, evaluate the effects of silibinin on the expressions of collagen types I and III, and assess its effects on the suppression of the mTOR signaling pathway." (PMID 37762688, 2023). "The article also explores the impact of several signaling pathways within the immune microenvironment on keloid formation, including the transforming growth factor β pathway (TGF-β), PI3K/Akt/mTOR signaling pathway, Wnt/β-catenin signaling pathway, and Notch signaling pathway." (PMID 40718487, 2025). "In addition to cells, several related signaling pathways have also been confirmed to play crucial roles in the pathogenesis of keloids, including TGF-βsignaling pathway, PI3K/Akt/mTOR signaling pathway, Wnt/β-catenin signaling pathway, and Notch signaling pathway." (PMID 40718487, 2025).
malnutrition (25 papers, 2012 to 2025). Inadequate nutrition resulting from poor diet, malabsorption, or abnormal nutrient distribution. "Despite the findings of the study, that associate certain key components of the mTOR pathway with childhood malnutrition, there are a number of limitations to our findings." (PMID 35458174, 2022). "GCN2K and mTOR are related to each other and jointly assess nutritional deficiency (GCN2K) and adequacy (mTOR)." (PMID 33552055, 2020). "Nutritional deficiency can lead to cell growth inhibition, which is partially achieved by relying on the mammalian target of rapamycin (mTOR) signaling pathway." (PMID 31803616, 2019). "There are multiple regulatory mechanisms of autophagy and the most studied mechanism, PI3K/AKT/mTOR pathway, is activated under normal nutritional conditions leading to autophagy inhibition, however, during nutritional deficiency, PI3K/AKT/mTOR pathway is inhibited leading to autophagy occurrence." (PMID 37404761, 2023). "Resistance training activates the PI3K/Akt/mTOR signaling axis, which promotes protein synthesis, muscle fiber hypertrophy, and preservation of lean body mass—crucial adaptations for counteracting the muscle catabolism associated with surgical stress and malnutrition." (PMID 40806373, 2025). "In this study, we aimed to explore a potential aberration in the mTOR pathway with the phenotype of childhood malnutrition." (PMID 35458174, 2022). "Our findings provide key insights into possible down-modulation in the overall activity of the mTOR pathway in childhood malnutrition." (PMID 35458174, 2022). "We aimed to elucidate possible implications for potential aberrations in the mTOR pathway with childhood malnutrition." (PMID 35458174, 2022). "Poor vasculature results in hypoxia and malnutrition of tissues, which creates a stressful situation for the cells, which is known to enhance the mTOR signalling." (PMID 29304116, 2018). "By day 3 of malnutrition, the signaling activities of β-catenin and mTOR pathways were essentially reduced to the basal level." (PMID 25184386, 2014). "The malnutrition period reduced the muscle protein synthesis rate and mTOR/p70S6kinase/4eBP1 activation, and only the 10%-pollen diet was able to restore these parameters." (PMID 25470375, 2014). "Studies should investigate newer immunological parameters in malnutrition, like expression of innate pattern recognition receptors (as the Toll-like receptor), the lectin pathway of the complement system and mTOR expression and activity." (PMID 25153531, 2014). "The use of biopsy samples from the upper GI tract or the epiphyseal plate could have been a more suitable representative to study the potential deregulations in the mTOR pathway in childhood malnutrition." (PMID 35458174, 2022). "However, there is a distinct lack of literature that provides evidential proof regarding the potential role of the mTOR pathway in childhood malnutrition." (PMID 35458174, 2022). "In addition, a high-altitude environment can also regulate autophagy through the mTOR-related signaling pathway as mTOR kinase can be inhibited under conditions such as malnutrition, decreased ATP levels, and hypoxia." (PMID 35620712, 2022). "If this is correct, we can only speculate on how malnutrition is sensed in the gut, whether by mTOR or by intestinal cell kinase." (PMID 31229436, 2019). "Lack of data regarding the protein expression hinder us from having conclusive evidence regarding possible deregulations of the mTOR pathway in childhood malnutrition, since post-transcriptional and post-translational modifications of the products of the gene expression may occur." (PMID 35458174, 2022). "Our study aimed at investigating if long-term leucine supplementation could modulate GH-insulin-like growth factor (IGF)-1 system function and mammalian target of rapamycin (mTOR)-related signal transduction in skeletal muscles in a rat model of severe malnutrition." (PMID 25909895, 2015).
malnutrition (continued). "Since calorie restriction and fasting are not so efficient as rapamycin in inhibition of mTOR and also may cause malnutrition, rapamycin at low and/or intermittent doses may be even a better choice for prevention of side effects of chemotherapy." (PMID 23565531, 2012). "However, chronic or severe malnutrition leads to persistent mTOR suppression and elevated Treg dominance, which may inhibit effector lymphocyte proliferation and reduce host defense capacity, thereby increasing susceptibility to secondary infections such as VAP in clinical settings." (PMID 40901298, 2025). "Thus, the deregulation of certain key components of the mTOR pathway in childhood malnutrition may be attributed to a combinatory effect of increased levels of pro-inflammatory cytokines leading to reduced levels of IGF-1 and growth hormone and a deficiency of essential amino acids in circulation." (PMID 35458174, 2022). "Therefore, the purpose of this study was to investigate if long-term dietary supplementation with different doses of leucine could regulate GH-IGF-1 system function and mammalian target of rapamycin (mTOR)-related signal transduction in skeletal muscles in a rat model of severe malnutrition." (PMID 25909895, 2015). "Murine studies have shown that moderate caloric restriction without inducing overt malnutrition suppressed mTOR signaling, drove metabolic reprogramming toward glycolysis and autophagy, and attenuated excessive lymphocyte recruitment and inflammation." (PMID 40901298, 2025).
T-cell acute lymphoblastic leukemia (25 papers, 2010 to 2025). Acute lymphoblastic leukemia of T-cell origin. "Hypoxia-induced decreases in mTOR activity are also described in T-cell acute lymphoblastic leukemia, which also develops within the BM." (PMID 40938732, 2025). "mTOR inhibition and subsequent miR21 upregulation was shown to repress Cdk6 in T cell acute leukemia, resulting in decreased tumor proliferation." (PMID 35572197, 2022). "The mTOR inhibitor BEZ235 overcame glucocorticoid resistance in pediatric T-cell ALL (T-ALL) by increasing BIM expression." (PMID 26919107, 2016). "Constitutively active PI3K/Akt/mTOR signaling is observed in many types of solid and blood tumors, including T-cell acute lymphoblastic leukemia (T-ALL), where it portends a poorer prognosis and negatively influences response to therapeutic treatments." (PMID 25788264, 2015). "Moreover, the mTOR inhibitor, everolimus, was reported to abrogate resistance to dexamethasone in T-cell acute lymphoblastic leukemia cells by reducing G6PD protein levels and enhancing ROS levels." (PMID 37802999, 2023). "Our findings suggested that multiple Akt targeting by drugs with different mechanism of action could represent a new promising treatment for T-cell acute lymphoblastic leukemia patients with PI3K/Akt/mTOR pathway hyperactivation." (PMID 25788264, 2015).
angiosarcoma (24 papers, 2014 to 2025). A malignant tumor arising from the endothelial cells of the blood vessels. "It is reported that inhibition of PI3K/mTOR signaling pathway suppress growth of angiosarcoma in vivo using mouse model." (PMID 35256687, 2022). "By contrast, in canine hemangiosarcomas only 35% of samples had weak to moderate expression of p-mTOR." (PMID 35883491, 2022). "One study found activating mutations in PIK3CA in 40% of tumors while other investigators describe elevated levels of phosphorylated S6 in 100% and phosphorylated 4EBP1 in 88% of angiosarcomas, both of which are downstream effectors of mTOR." (PMID 29872503, 2018). "The results observed here are consistent with one study performed with a monoinhibitor of mTOR (rapamycin) in human angiosarcoma, where pathway inhibition was found to reduce cell proliferation in vitro." (PMID 30011343, 2018). "Mutations in KRAS have been found in 13–60% of angiosarcomas as well, leading to activation of both the PI3K/mTOR and MAPK pathways." (PMID 29872503, 2018). "Using a systematic approach, we have discovered that angiosarcomas are insensitive to mTOR inhibition." (PMID 25955301, 2015). "PI3K inhibitor and mTOR inhibitor are possible targets for angiosarcoma therapy." (PMID 38015377, 2023). "Interestingly, a trial of the mTOR inhibitor everolimus in patients with recurrent soft tissue sarcomas reported that the progression free rate was highest in angiosarcoma patients compared to patients with other high-grade sarcomas." (PMID 29872503, 2018). "We observed that angiosarcomas are insensitive to mTOR inhibition." (PMID 25955301, 2015). "Previous studies on the genomic landscape of angiosarcoma have described recurrent somatic mutations of angiogenic signaling pathway genes, including KDR, PTPRB, and PLCG114–18, as well as genes involved in oncogenic signaling pathways such as MAPK, PIK3CA/AKT/mTOR, and TP5319,20." (PMID 37106027, 2023). "The pathogenesis of angiosarcoma is probably also related to other genes, including CIC gene rearrangement, increased expression of the MYC gene and FLT-4 gene, and mutations of PTPRB and PLCG1, but the present study focused on the PD-1/PD-L1 and PI3K/mTOR signaling pathways." (PMID 34397726, 2021). "The dual PI3K/mTOR inhibitor, VDC597, dose-dependently reduces cell proliferation, invasion, and vascular endothelial growth factor production in canine hemangiosarcoma." (PMID 36816969, 2023). "We investigated the activation status of the PI3K/mTOR and MAPK pathways in murine angiosarcoma and found both to be active in all three genetic combinations." (PMID 29872503, 2018). "The dramatic response to combined in vivo mTOR and MEK inhibition which we have observed in our genetically engineered animal model for angiosarcoma should renew efforts to design clinical trials for patients with this disease." (PMID 29872503, 2018). "The currently available genetically engineered mouse models of angiosarcoma are driven by knockout of Notch pathway components or FoxO,170 or overactivation of the mTOR pathway, but these may not reflect findings in human angiosarcomas." (PMID 29872699, 2017). "Thus, the PI3K/AKT/mTOR and MEK/ERK signaling pathways may converge on an angiogenesis-related target required for angiosarcoma progression." (PMID 25955301, 2015).